ENSG00000297354 (novel transcript, sense overlapping PPIAL4D)
Gene: Long non-coding RNA gene on chromosome 1 (145,235,259 to 145,281,295, reverse strand). Ensembl gene ENSG00000297354.
Gene Ontology:
Molecular function: pre-mRNA 5'-splice site binding
Biological process: mRNA 5'-splice site recognition
Cellular component: U1 snRNP